SSX8P (SSX family member 8, pseudogene)
Description:
Could act as a modulator of transcription.
Synonyms: formerly SSX8
Gene: Transcribed unprocessed pseudogene on chromosome X (52,624,998 to 52,632,891, forward strand). Ensembl gene ENSG00000157965.